PPARA (peroxisome proliferator activated receptor alpha)
Diseases named in the same sentence as PPARA in open-access papers (continued):
Sharing a sentence is not in itself a finding about the gene and the disease.
cyst (6 papers, 2017 to 2025). A sac-like closed membranous structure that may be empty or contain fluid or amorphous material. "The imposed burden placed by nephron loss stimulates signaling including PPARα, AMPK, and mTORC1, leading to tubular hypertrophy and cyst formation, thereby contributing to CKD progression." (PMID 40089478, 2025). "In a Pkd1RC/RC mouse model of ADPKD, treatment with PPARα agonist fenofibrate increased mitochondrial function as well as slowed cyst growth and the proliferation of cystic epithelial cells." (PMID 34566674, 2021). "In human and mouse renal cysts, the whole network of PPARα-target genes was shown to be downregulated, while increasing Pparα expression was able to attenuate cyst growth." (PMID 34566674, 2021). "We have recently shown that PPARA upregulation is sufficient to improve cyst metabolism and attenuate cyst growth." (PMID 30760828, 2019). "Fenofibrate treatment increased Pparα expression in Pkd2-KO kidneys, whereas it reduced kidney-weight-to-body-weight ratio, cyst index, and proliferation suggesting that increasing Pparα expression attenuates cyst growth." (PMID 28205547, 2017). "Conversely, we tested whether increasing Pparα expression attenuates proliferation and cyst growth." (PMID 28205547, 2017). "PPARα is the key regulator of mitochondrial oxidative phosphorylation (OXPHOS) and fatty acid oxidation (FAO), suggesting that miR-17 promotes cyst growth through affecting the mitochondrial metabolism in renal epithelial cells." (PMID 33809516, 2021). "However, although the PPARα agonist fenofibrate has been shown to slow cyst growth in PKD mouse models, the binding affinity of pioglitazone to PPARα is likely too low to sufficiently activate PPARα when used at clinically relevant doses." (PMID 32015419, 2020). "Our results have shown that miR-17 and miR-19 directly inhibit Pparα expression in cystic kidneys, but whether reducing Pparα gene dosage is sufficient to promote cyst growth is not known." (PMID 28205547, 2017).
dry eye (6 papers, 2019 to 2023). "This implies PPARα activation could have potential for use as a preventive agent in patients with high risk of dry eye." (PMID 33086679, 2020). "The greatest differences are seen in neutrophils, myeloid (macrophage and monocyte) and cDC2 cells and include IL-6, LPS-stimulated MAPK, NFkB, IL-17, and PPARα/RXRα signaling pathways that contain mediators relevant to dry eye pathogenesis." (PMID 35402439, 2022). "In the corneal epithelium of mice with dry eyes by sleep deprivation, downregulation of PPARα expression was detected, and fenofibrate increased PPARα expression in cultured corneal epithelium sheets and restored microvilli morphology." (PMID 33086679, 2020). "Consistent with our findings, PPARα is also downregulated in experimental mouse models of LG inflammation induced by high-fat diets or obstructive sleep apnea that lead to lipid accumulation and dry eye symptoms." (PMID 36901740, 2023).
immunotoxicity (6 papers, 2013 to 2025). "PFASs have been reported to activate PPARα and, therefore, the role of PPARα in PFAS-induced immunotoxicity has been studied." (PMID 36326898, 2022). "In human white blood cells in vitro, mechanistic studies of PFC-induced suppression of cytokine secretion demonstrated that PPARα activation was involved in the PFOA-induced immunotoxicity, while other pathways appeared responsible in regard to the effects of PFOS." (PMID 23597293, 2013). "In addition, PPARα-independent pathways may partially account for PFOS immunotoxicity as well." (PMID 31238913, 2019). "While human PPARα expression is significantly less than that of rodents, current evidence suggests that both PPARα-dependent and -independent pathways may be relevant to PFC immunotoxicity." (PMID 23597293, 2013).
kidney inflammation (6 papers, 2012 to 2025). "In the Fib(−) group, the induction of anti-Thy1 nephritis decreased the mRNA expressions of PPARα and ACOX, a result that was identical to the results of the PPRE binding assay and suggesting the deterioration of glomerular PPARα." (PMID 22675338, 2012). "In the Fib(−) group, the induction of anti-Thy1 nephritis obviously decreased the PPRE binding activity of PPARα at days 7 and 14 in a time-dependent manner." (PMID 22675338, 2012). "The induction of anti-Thy1 nephritis decreased these expressions in each group; however, the PPARα and ACOX expressions of both clofibrate treatment groups remained over the baseline level of the control rats." (PMID 22675338, 2012). "The developmental process of anti-Thy1 nephritis decreased glomerular PPARα expression and weakened its function, while the pretreatment with an appropriate dose of clofibrate appeared to outweigh this deterioration." (PMID 22675338, 2012). "To investigate whether PPARα activation improves the disease activity of MsPGN, we examined the protective effects of a PPARα agonist, clofibrate, in a well-established model of human MsPGN, anti-Thy1 nephritis, for the first time." (PMID 22675338, 2012). "Moreover, compared with those in young rats, ROS levels and inflammation were increased in the kidneys of elderly rats, while MHY3200 (a PPARα agonist) intervention could effectively activate PPARα and inhibit NF-κB, thus inhibiting the occurrence of kidney inflammation." (PMID 37397494, 2023).
osteosarcoma (6 papers, 2012 to 2024). A usually aggressive malignant bone-forming mesenchymal neoplasm, predominantly affecting adolescents and young adults. "On the other hand, TRIM46 acts as an oncogene in osteosarcoma by interacting with and ubiquitinating peroxisome proliferator-activated receptor alpha (PPARα), resulting in the activation of the NF-κB signaling pathway." (PMID 33717417, 2021). "However, in the present results, only PPARδ and PPARγ, but not PPARα, expressions were increased in MG63 osteosarcoma cells in response to high shear force stimulation, and further results found that only PPARδ is involved in mediating SCD-1 upregulation of high shear force stimulation." (PMID 32630668, 2020).
retinal ischemia (6 papers, 2021 to 2024). A ischemic disease that involves the retina. "Two PPARα agonists (fenofibrate and pemafibrate) have been examined in many experimental models of retinal ischemia." (PMID 38791541, 2024). "We revealed that the consecutive oral administration of pemafibrate, a selective PPARα modulator, suppressed pathological retinal gliosis and functional neuronal deficits in a murine model of retinal ischemia by UCCAO." (PMID 34502311, 2021). "Previously, pemafibrate, a selective peroxisome proliferator-activated receptor alpha modulator, was nominated as a promising drug in retinal ischemia." (PMID 34502311, 2021). "Multiple studies have suggested that PPARα agonists could become possible promising drugs for retinal ischemia, and activation of PPARα by fenofibrate has been shown to suppress pathological angiogenesis in the retina in vivo and in vitro." (PMID 33799938, 2021). "Modulating PPARα may improve retinal ischemia in animals and humans." (PMID 38791541, 2024). "Moreover, PPARα agonists reduced hypoxia-induced HIF-1α expression and activity in cancer cells, and improved ischemic retina diseases through decreasing HIF-1α in endothelial cells." (PMID 34268320, 2021).
rhabdomyolysis (6 papers, 2016 to 2025). Necrosis or disintegration of skeletal muscle often followed by myoglobinuria. "Compared with conventional fibrates, pemafibrate is considered to have a lower risk of rhabdomyolysis and renal dysfunction, probably because it is a selective PPARα modulator of hepatic lipid metabolism and is excreted by the liver." (PMID 39802168, 2025). "The most commonly used agents are statins (3-hydroxy-3-methyl glutaryl coenzyme A reductase inhibitors) and fibrates (peroxisome proliferator-activated receptor-alpha agonists), these agents, while effective, cause a markedly increased risk of myopathy and rhabdomyolysis." (PMID 27495782, 2016).
skin cancer (6 papers, 2008 to 2023). "As PPARα upregulation has a partial role in skin cancer therapy, the authors investigated this mechanism for UA." (PMID 37893218, 2023). "Owing to PPARα upregulation, UA can be employed in pharmaceutical and cosmeceutical dermatology and skin cancer." (PMID 37893218, 2023). "Skin cancer can also be targeted by UA, which activates the peroxisome proliferator activated receptor α (PPARα) and AMPK in mouse squamous cell carcinoma Ca3/7 cells and mouse skin papilloma MT1/2 cells." (PMID 35887090, 2022). "Interestingly, UA’s agonistic effect on PPARα played a pivotal role in its cytotoxic activity against skin cancer through the AMPK pathway." (PMID 37893218, 2023). "It is worth noting that PPARα activators prevented DMBA/TPA-induced skin tumors when locally applied to mouse skin, and reduced UV-induced inflammation in human skin, which is a risk factor for further development of UV-induced skin cancers." (PMID 19125181, 2008). "The activation of PPARα by UA, however not through direct binding, led to the apoptosis of skin cancer cells that were previously treated with PPARα and AMPK inhibitors." (PMID 35887090, 2022).
Zinc deficiency (6 papers, 2010 to 2021). A deficiency of the essential metal Zinc; an essential cofactor for many enzymes. "Alcohol-induced inhibition of beta-oxidation is also mediated by the inhibition of PPAR-α (peroxisome proliferator-activated receptor alpha), which is downregulated directly via acetaldehyde- or CYP2E1-related oxidative stress, zinc deficiency, adenosine, and adipokine signaling." (PMID 34575850, 2021).
acute liver failure (5 papers, 2016 to 2022). Rapid deterioration of liver function causing encephalopathy and coagulopathy. "A previous study has revealed that PPARα activation decreased severe ER stress-induced hepatocyte apoptosis in acute liver failure." (PMID 35356086, 2022). "Peroxisome proliferator-activated receptor α (PPARα) is a key regulator to ameliorate liver injury in cases of acute liver failure (ALF)." (PMID 27482818, 2016).
adenoma (5 papers, 2007 to 2015). A neoplasm arising from the epithelium. "Since PPARα agonists are known to produce proliferative Leydig cell lesions (hyperplasia and adenoma) in the testes of rats, a relationship to treatment for these findings in the 50 mg/kg group cannot be ruled out." (PMID 28962433, 2015). "A significant reduction in PPARα expression is detected in human CRC specimens and UC patients' mucosa, suggesting PPARα as a therapeutic target to prevent adenoma formation also in IBD-induced cancer formation." (PMID 22991505, 2012).
bladder tumors (5 papers, 2012 to 2022). "A possible biological association exists, with a potential mechanism linked to the ‘predisposing’ capacity of peroxisome proliferator-activated receptor (PPAR) and/or PPARα agonists for bladder tumours." (PMID 22460763, 2012).
cocaine addiction (5 papers, 2023 to 2025). "BCP dual activation of PPARα and PPARγ, observed in our in vitro experiments and previously shown in cocaine addiction studies performed in vivo, highlights the possibility that BCP might behave as a dual PPARα/γ agonist like saroglitazar." (PMID 37047034, 2023).
colorectal tumors (5 papers, 2006 to 2023). "Human colorectal tumors have lower levels of PPARA mRNA and protein than nontumor tissues and loss of PPAR-α promotes colon carcinogenesis by increasing DNMT1 methyltransferase mediated methylation of p21 and PRMT6 methyltransferase mediated methylation of p27." (PMID 32973493, 2020). "MiR-506 was also involved in the chemo-response of ovarian and colorectal tumors via RAD51 and PPARα, respectively." (PMID 37051101, 2023).
dementia (5 papers, 2008 to 2023). Loss of intellectual abilities interfering with an individual's social and occupational functions. "The relevance of a potential beneficial effect of PPARα for dementia is supported by some studies showing that polymorphisms in PPARA gene encoding PPARα were associated with an increased risk of AD." (PMID 32422896, 2020). "We found a decreased PPARα protein levels by Western blotting in AD samples compared to non-dementia controls." (PMID 36711875, 2023).
endotoxemia (5 papers, 2012 to 2025). "In contrast to the suggested anti-inflammatory role of PPARα, Hill and colleagues observed, in a mouse model of endotoxemia, higher TNFα levels in animals treated with PPARα agonists." (PMID 35954274, 2022). "This suggests that LPS-induced lipid accumulation in the livers of aged rats was due to an increase in SREBP1c activity and a decrease in PPARα activity during endotoxemia." (PMID 25847140, 2015). "Regarding PPARα, treating mice model of endotoxemia with fenofibrate or Wy surprisingly elevated TNF-α levels in plasma." (PMID 23577023, 2013). "However, several observations also indicated that PPARα had beneficial effects against endotoxemia in humans." (PMID 23577023, 2013).
hepatocellular adenoma (5 papers, 2008 to 2023). A benign epithelial neoplasm arising from the hepatocytes. "PFOA induces hepatocellular adenomas and hepatocyte hypertrophy, bile duct hyperplasia, and hematopoietic cell proliferation in mice after prenatal exposure through PPARα-independent pathways." (PMID 35202277, 2022). "PFOA, like many other PPARα-agonists, induced hepatocellular adenomas, Leydig cell adenomas, and pancreatic acinar cell adenomas in rats." (PMID 29930891, 2018). "Additionally, we compared the mechanismsof tumorigenesis between wild-type mice and PPARα-nullmice using hepatocellular adenoma tissues of both genotyped mice." (PMID 18769559, 2008). "In PPAR α wild-type mice, Wyeth-14,643 was found to induce multiple hepatocellular adenomas and, sometimes, carcinomas, while it tested negative in PPARα-null mice." (PMID 36982734, 2023). "Interestingly, the gene expressions of apoptotic peptidaseactivating factor 1 and DNA-damage-inducible 45α (Gadd45α) were increased inthe hepatocellular adenoma tissues of wild-type mice exposed to DEHP, whereasthey were unchanged in corresponding tissues of PPARα-null mice." (PMID 18769559, 2008).
hypothyroidism (5 papers, 2020 to 2025). Abnormally low levels of thyroid hormone. "An opposite effect was observed in SCD1−/− mice, in which hypothyroidism caused a significant increase (by 36%) in PPARα protein levels." (PMID 33374300, 2020). "Protein levels of PGC1α decreased in WT Hypo mice and increased in SCD1−/− Hypo mice compared with respective controls, indicating that this factor is involved in the regulation of PPARα in the heart in hypothyroidism and that SCD1 deficiency affects PGC1α function." (PMID 33374300, 2020). "Another possibility is the activation of AMPK and PPARα by SCD1 deficiency in hypothyroidism." (PMID 33374300, 2020). "Overall, these results indicate that SCD1 deficiency increases FA uptake, in which PPARα and AMPK activation upregulate the FA transporter CD36, and oxidation in the heart in hypothyroidism." (PMID 33374300, 2020). "In such a setting, our results suggest that in hypothyroidism, the regulation of peroxisomal biogenesis in brown adipocytes may be a result of mutual action of both PPARα and PPARγ." (PMID 34571897, 2021).
left ventricular hypertrophy (5 papers, 2015 to 2025). Enlargement of the LEFT VENTRICLE of the heart. "Fenofibrate, another PPARα agonist, regresses left ventricular hypertrophy and increases the myocardium PPARα expression in spontaneously hypertensive rats." (PMID 29301869, 2018). "In addition to the established involvement of Noxs, downregulation of peroxisome proliferator-activated receptor-α (PPARα) is also recognised as an important mediator of pressure overload-induced left ventricular hypertrophy (LVH)." (PMID 32575797, 2020). "Systemic deletion of PPARα results in attenuated cardiac FAO rates and age-related cardiac fibrosis whereas mice with high levels of cardiac-specific PPARα overexpression show augmented fatty acid uptake and oxidation, accumulation of intracellular triglycerides, and left ventricular hypertrophy." (PMID 25815008, 2015).
lung diseases (5 papers, 2012 to 2024). "This review examined the role of PPAR agonists, specifically PPARα, PPARβ, and PPARγ, in combating inflammatory and oxidative stress cascades in various pulmonary disorders." (PMID 38360670, 2024).
malnutrition (5 papers, 2014 to 2026). Inadequate nutrition resulting from poor diet, malabsorption, or abnormal nutrient distribution. "When PPARα is activated by free fatty acids, intracellular β-oxidation is enhanced, and ATP and ketone body production are increased, so that PPARα can use free fatty acids to provide the energy required by the body in the state of nutritional deficiency." (PMID 40650120, 2025). "A previous study in rats also demonstrated that maternal malnutrition leads to alterations in PPAR gene expression (PPARα and PPARγ) in the offspring at 18 months of age." (PMID 25158235, 2014). "During fasting and malnutrition, metabolic adaptations are triggered by PPARα (peroxisome proliferator-activated receptor alpha) to minimize the use of protein and carbohydrates as fuel to allow survival during long periods of energy deprivation and lipolysis pathways are engaged instead." (PMID 31619276, 2019).
mastitis (5 papers, 2012 to 2026). Inflammation of breast tissue during lactation or postpartum due to an obstructed duct or infection. "We evaluated effects of fenofibrate, a peroxisome proliferator-activated receptor α (PPARα) agonist, on M. bovis infection, using both bovine mammary epithelial cells and a murine mastitis model." (PMID 41602117, 2026). "Based on Western blotting in the present research, the mammary glands with subclinical bovine mastitis exhibited obviously increased PPARα expressions but reduced PPARδ/β and PPARγ expressions, in contrast to the healthy mammary glands." (PMID 39765775, 2024).
nonalcoholic fatty liver (5 papers, 2017 to 2022). "Nonalcoholic fatty liver(NAFLD) caused by abnormal hepatic fat deposition is due to more than just impaired adenosine-monophosphate-activated protein kinase (AMPK)-peroxisome proliferator-activated receptor alpha(PPAR-α) signaling." (PMID 28376799, 2017).
overnutrition (5 papers, 2010 to 2023). An imbalanced nutritional status resulting from excessive intake of nutrients. "In conditions of overnutrition and physical inactivity, availability of cellular fatty acids stimulate ligand–dependent PPARα/δ transcription factors which, in turn, induce transcription of genes responsible for β-oxidation." (PMID 20369014, 2010). "Interestingly, GR and PPARα are noncore clock components under circadian control that show enhanced circadian peak activity in overnutrition models, explaining the induction of Mfsd2a expression during the early stages of HFD challenge shown in the current study." (PMID 37463052, 2023).
prediabetes (5 papers, 2021 to 2024). "Based on this, we believe that the relieving effect of HDB on prediabetes may be related to the AMPK/PGC-1α/PPARα signaling pathway and GLUT-4 protein." (PMID 37391779, 2023). "This study demonstrates that LJF and CGA exert hypoglycemic and lipid modulation capacity to prevent prediabetes may through the CTRPs-AdipoRs-AMPK/PPARα axes and promoting ELOVL6 protein expression." (PMID 36313074, 2022). "Thus, we hypothesized that LJF extracts and its primary active ingredient CGA ameliorate prediabetes through CTRPs- AdipoRs-AMPK/PPARα Axes." (PMID 36313074, 2022). "Thus, the effect of PPARα agonists on cardiac function is contradictory in different animal studies, and intervention studies in prediabetes and T2DM are not performed." (PMID 34827678, 2021).